LGR5 (leucine rich repeat containing G protein-coupled receptor 5)
Diseases named in the same sentence as LGR5 in open-access papers (continued):
Sharing a sentence is not in itself a finding about the gene and the disease.
cervical carcinoma (continued). "In addition, the DSF/Cu complex could inhibit the expression of stemness markers and suppress the cisplatin-resistant LGR5+ stem-like population in cervical cancer cells." (PMID 35534815, 2022). "Therefore, elevated LGR5 expression could enhance the tumorigenic capacity of cervical cancer cells in vivo." (PMID 28880275, 2017). "Also, this prompts us that LGR5 may be used as a potential therapeutic target for the treatment of cervical carcinoma with high expressing of LGR5." (PMID 28880275, 2017). "Furthermore, we found that the increased tumorsphere-forming efficiency induced by LGR5 could be regulated through the inhibition or activation of the Wnt/β-catenin pathway in cervical cancer cells." (PMID 28880275, 2017). "Finally, we found that the increased tumorsphere-forming efficiency induced by LGR5 could be regulated through the inhibition or activation of the Wnt/β-catenin pathway in cervical cancer cells." (PMID 28880275, 2017). "Therefore, we propose a hypothesis in which LGR5 potentiates Wnt/β-catenin signaling, accelerates the cell cycle, and promotes cell proliferation, eventually leading to the progression of cervical cancer." (PMID 25193857, 2014). "Our findings showed that LGR5 was progressively expressed in cervical carcinogenesis, and LGR5 expression promoted the proliferation and tumor formation of cervical cancer cells by potentiating the Wnt/β-catenin pathway, indicating that LGR5 may be a potential therapeutic target in cervical cancer." (PMID 25193857, 2014). "Therefore, we hypothesized that LGR5 might also contribute to cervical carcinogenesis, and in this study, we investigated the role of LGR5 in cervical cancer." (PMID 25193857, 2014). "Therefore, further investigation is necessary to clarify whether LGR5 enhances the tumor formation of cervical cancer cells through the regulation of cervical cancer stem cells." (PMID 25193857, 2014). "Evidence indicates that various oncogenes (e.g., LGR5 and DAX1) and suppressor genes (e.g., KLF4 and SLUG) exhibit abnormal expression during cervical carcinoma progression, highlighting the importance of genetic factors." (PMID 39518154, 2024). "However, to our knowledge, the role of LGR5 in cervical cancer remains unclear." (PMID 25193857, 2014). "Furthermore, a cell cycle analysis by FACS revealed that increased LGR5 expression resulted in a significant increase in the percentage of cells in S phase and a concomitant decrease in the percentage of G0/G1 phase cells, suggesting that LGR5 accelerates the cell cycle in cervical cancer cells." (PMID 25193857, 2014). "We for the first time found that the expression of LGR5 was gradually increased from normal cervix (17%) to cancer in situ (65%) and invasive cervical cancer (84%), suggesting that LGR5 may function to promote the development and progression of cervical cancers, as in other types of cancers." (PMID 25193857, 2014). "However, the role of LGR5 in cervical cancer remains unclear." (PMID 25193857, 2014). "In addition, other transcription factors such as NANOG, OCT4, LGR5, and EZH2 promote tumor formation in cervical cancer." (PMID 33947962, 2021). "According to this study, the DSF/Cu complex exhibited equivalent effect whether LGR5-positive cervical cancer stem-like cells or LGR5-negative cells both in vitro and in vivo systems." (PMID 35534815, 2022). "Together, these results from the tumor formation assays in NOD/SCID mice suggest that cervical cancer cells with elevated LGR5 expression have a more rapid tumor growth rate, shorter tumor latency, lower tumor-free rate and higher frequency of tumor-initiating cells than LGR5-negative cells." (PMID 28880275, 2017). "However, there are no reports identifying whether LGR5 is able to enhance the proliferation and tumor formation of cervical cancer cells by activating Wnt/β-catenin signaling." (PMID 25193857, 2014).
lymph node metastasis (23 papers, 2011 to 2025). "This is congruent with the clinical observation that lymph node metastasis often precedes lung metastasis in CCA patients, and the association of LGR5 expression with lymph node metastases in other tumor types." (PMID 36741736, 2022). "46% of samples revealed high Lgr5 expression which was associated with lymph node metastasis, size of the tumor and triple negative status." (PMID 31814939, 2019). "In these tumors, Lgr5 has been associated with depth of invasion, lymph node metastasis and distant metastasis." (PMID 28404917, 2017). "In summary, overexpression of Lgr5 was significantly correlated with lymph node metastasis, tumor stage and response to chemotherapy, while high levels of Lgr5 expression were also associated with poor survival in patients with SCCE." (PMID 24666414, 2014). "Also, the expression of LGR5 in lymph node metastases was associated with lymph vessel invasion (p = 0.001) (Supplementary )." (PMID 31827644, 2019). "Furthermore, LGR5 expression was associated with a high stage and lymph node metastasis." (PMID 33676447, 2021). "We assessed the prognostic value of LGR5 expression in lymph node metastasis by Kaplan–Meier analysis and the log‐rank test." (PMID 38787285, 2024). "The lower expression of Lgr5 was significantly correlated with the presence of lymph-node metastases (p = 0.011), while high expression of Lgr5 was statistically significant in vascular invasion in examined cancer tissue samples (p = 0.027)." (PMID 32671503, 2020). "Our results suggest that the expression of Lgr5 is significantly lower in CRC with lymph-node metastases." (PMID 32671503, 2020). "Our results suggest a strong relationship between CSC marker Lgr5 and vascular invasion, presence of lymph-node metastasis, and overall poor survival." (PMID 32671503, 2020). "Statistical analysis showed significant differences in expression of Lgr5 and the presence of lymph-node metastases (p = 0.011)." (PMID 32671503, 2020). "In conclusion, our results suggested a strong relationship between CSC marker Lgr5 and vascular invasion, presence of lymph-node metastasis, and poor survival." (PMID 32671503, 2020). "Lgr5 expression was significantly correlated with lymph node metastasis, increased depth of invasion, increased tumor size, advanced differentiation, higher AJCC stage and poorer survival." (PMID 28404917, 2017). "Lgr5 expression was significantly correlated with lymph node metastasis, increased depth of invasion, increased tumor size, advanced differentiation, higher AJCC stage and poor survival." (PMID 28404917, 2017). "As a biomarker, LGR5 positivity predicts lymph node metastasis with 95.5% sensitivity (95% CI 88.8%-98.7%) and 61% specificity (95% CI: 48.4%–72.4%) and has a negative predictive value (NPV) of 91.3% (95% CI 79.2%–97.5%) for lymph node metastatic disease." (PMID 26416247, 2015). "Previous studies have demonstrated that elevated LGR5 expression significantly correlates with lymphatic invasion, vascular invasion, tumor depth, lymph node metastasis, and tumor recurrence." (PMID 25192390, 2014). "High Lgr5 expression was significantly correlated with lymph node metastasis (p = 0.003), late stage (p = 0.003) and unfavorable response to chemotherapy (p = 0.013) according to RECIST 1.0 criteria." (PMID 24666414, 2014). "Significant positive correlations were found between Lgr5 expression and histological grade (P=0.001), depth of invasion (P=0.001), lymph node metastasis (P=0.001), and distant metastasis (P=0.004)." (PMID 23153436, 2012). "Lgr5 was positively correlated with histological grade (P=0.001), depth of invasion (P=0.001), lymph node metastasis (P=0.001), distant metastasis (P=0.004), pTNM stage (P=0.001), and Ki-67 (r=0.446, P=0.001)." (PMID 23153436, 2012). "Increased expression of Lgr5 was significantly correlated with depth of invasion, lymph node metastasis, and distant metastasis." (PMID 23153436, 2012).
lymph node metastasis (continued). "Although the mRNA expression of genes involved in EMT induction and metastasis is associated with the mRNA expression of all investigated LGR5 transcript variants in this study, only OSCC patients with a high tumoral LGR5Δ5 level have a significant higher risk of regional lymph node metastasis." (PMID 30770730, 2019). "Additionally, both positive Lgr5 expression and a high TB grade were significantly correlated to the depth of tumor invasion, lymph node metastasis, pTNM stage, and perineural invasion (P < 0.01)." (PMID 30046385, 2018). "Lgr5 expression was significantly correlated with lymph node metastasis (χ2 = 8.351, P = 0.040), increased depth of invasion (χ2 = 15.95, P < 0.0001), increased tumor size (χ2 = 8.819, P = 0.012), advanced differentiation (χ2 = 14.249, P = 0.001) and higher AJCC stage (χ2 = 4.99, P = 0.025)." (PMID 28404917, 2017). "LGR-5 was known to be correlated with CRC lymph node metastasis." (PMID 27776350, 2016). "The relationship between Lgr5 expression and clinicopathological parameters was analyzed, and the results showed that Lgr5 overexpression was significantly correlated with deep invasion, lymph node metastasis,distant metastasis, and advanced AJCC stage." (PMID 26674601, 2015). "Multivariable analysis confirmed that negative LGR5 expression was an independent risk factor for peritoneal recurrence (hazard ratio (HR) 2.79, p = 0.005) in addition to poor differentiation, positive lymph node metastasis, preoperative carcinoembryonic antigen > 5 ng/mL and anastomotic leakage." (PMID 31000786, 2019). "Our study showed that increased Lgr5 expression is statistically significantly related to a lack of lymph-node metastasis, presence of vascular invasion, and low survival rate in CRC." (PMID 32671503, 2020). "Our results indicated that high levels of Lgr5 expression were significantly correlated with lymph node metastasis and late stage (stage III/IV), suggesting that high expression of Lgr5 might predict a poor prognosis." (PMID 24666414, 2014). "Multivariate analysis using the Cox Proportional Hazards Model demonstrate lymph node metastasis and grading but not LgR5 expression as independent prognostic factors in all (n = 60) EACs (LN positive: Exp (b) 9.1861; 95% CI of Exp (b) 2.0665 - 40.8346; p = 0.003746." (PMID 21345220, 2011).
basal cell carcinoma (21 papers, 2011 to 2026). A carcinoma involving the basal cells. "This evidence suggests a potential role for LGR5 in the regulation of glioma cell growth and proliferation which are in agreement with previous studies concerning basal cell carcinoma and Ewing sarcoma." (PMID 24172981, 2014). "We also confirmed LGR5 expression in tumors that arose from these tissues, such as basal cell carcinoma and colonic adenoma, as reported in previous studies." (PMID 24340024, 2013). "Notably, reduced proliferation upon WNT activation in TNBC parallels findings in LGR5+ basal cell carcinoma models, in which therapy-induced WNT activity drives a slow-proliferative phenotype." (PMID 41117706, 2026). "Additionally, nuclear IκB-kinase α (IKKα) could directly bind to the promoters of inflammation factors and LGR5, which upregulates Lgr5 expression in turn through the activation of STAT3 signaling pathway during cancer progression of basal cell carcinomas." (PMID 31358061, 2019). "Basal cell carcinoma has also been shown to express the epithelial stem cell markers CK19, LGR5, LRIG1, and SOX9." (PMID 34331569, 2021). "It was reported that epidermal cells positively stained with LGR5, one of the crucial markers of SCs in the epidermis, might be BCC’s cell origin, and the LGR5-positive tumor population is closely related to basal cell carcinoma relapse." (PMID 37325632, 2023). "The Lgr5 promoter also targets epithelial stem cells in skin and intestine, and while we previously showed that expression of GLI2A in this cell population in skin gives rise to basal cell carcinomas, we did not detect grossly apparent tumors in intestines of iLgr5;GLI2A mice." (PMID 26859571, 2016).
glioma (21 papers, 2014 to 2024). A benign or malignant brain and spinal cord tumor that arises from glial cells (astrocytes, oligodendrocytes, ependymal cells). "Firstly, LGR5 expression was immunohistochemically evaluated in 54 resected gliomas of different pathologic grades, and its association with Ki-67 was evaluated." (PMID 24172981, 2014). "LGR5 has been implicated in promoting the glioma stem cell phenotype." (PMID 29428975, 2018). "Among gene targets of probes demonstrating a positive correlation between 5hmC and increased gene expression in IDH1 mt tumors (Group 1) were several genes implicated in glioma pathogenesis, including leucine-rich repeat containing G protein-coupled receptor 5 (LGR5)." (PMID 29428975, 2018). "Glioma proliferation is associated with the expression of functional proteins such as decoy receptor 3 (DcR3), a member of the tumor necrosis factor receptor super-family, and leucine-rich repeat containing G protein-coupled receptor 5 (LGR5)." (PMID 27683117, 2016). "We aimed to ascertain whether LGR5 expression is associated with the proliferation of glioma cells." (PMID 24172981, 2014). "We obtained similar results with LGR5 expression in brain tissue and brain cancers (glioblastoma and low-grade glioma; LGG)." (PMID 39169164, 2024). "It was reported that the new functional glioma stem cell marker LGR5 played a role in glioma by promoting EMT31." (PMID 37863960, 2023). "For example, LGR5 acts as a glioma stem cell marker and promotes EMT through activating the Wnt/β-catenin pathway." (PMID 34539899, 2021). "LGR5, a receptor for R-spondins, promotes epithelial-mesenchymal transition by activating the Wnt/β-catenin pathway in glioma." (PMID 34880901, 2021). "Meanwhile, LGR5 has also been reported as a putative marker for CSCs in several types of cancers, e.g. basal cell carcinoma, glioma, and gastrointestinal cancers." (PMID 32382005, 2020). "Since JQ1-sensitive cells express high levels of both OLIG2 and LGR5, we anticipate that BET inhibition specifically targets the proneural glioma stem cell niche and makes these cells even more susceptible to genotoxic effects of TMZ." (PMID 31754113, 2019). "LGR5 is an epithelial stem cell marker that is involved in promoting tumorigenicity and invasion of glioma stem cells." (PMID 31754113, 2019). "In this study, we determined the stemness properties of LGR5+ and LGR5− glioma cells sorted by fluorescence-activated cell sorting (FACS)." (PMID 30208924, 2018). "The expression levels of CD133, CD44, CD24, CD90 and EpCAM were examined in LGR5+ and LGR5− U251 and 8591 glioma cells by FCM." (PMID 30208924, 2018). "(b) Fluorescence-activated cell sorting (FACS) of LGR5+ cells in U251 glioma cells and 8591 primary glioma cells." (PMID 30208924, 2018). "Although LGR5 has been identified as a prognostic factor in many tumors, there are few studies on the prognostic value of LGR5 in glioma." (PMID 30208924, 2018). "Our FCM analysis revealed that LGR5+ glioma cells displayed significantly higher expression of these CSCs markers, indicating that LGR5+ glioma cells have stronger stem cell characteristics than LGR5− cells." (PMID 30208924, 2018). "We found that LGR5+ glioma cells possessed considerably enhanced expression of CD133, CD44, CD90, CD24, and EpCAM." (PMID 30208924, 2018). "The expression levels of LGR5, Ki67 and N-cadherin were determined in 268 human glioma specimens by IHC." (PMID 30208924, 2018). "To evaluate the effect of LGR5 on glioma in vivo, we injected shRNA-LGR5/U87, shRNA-Ctr/U87 and untransfected U87 cells into nude mice to develop orthotopic tumors." (PMID 24172981, 2014). "The aim of the present study was to investigate the relationship between LGR5 expression and pathological grade in glioma, and the impact of LGR5 on the proliferation of glioma cells in vitro and in vivo." (PMID 24172981, 2014).
glioma (continued). "The data showed that LGR5 was highly expressed in all of the glioma cell lines at the protein and mRNA levels but the results did not achieve a significant difference." (PMID 24172981, 2014). "In the present study, we confirmed the expression of LGR5 in human gliomas and its correlation with pathologic grade and proliferation." (PMID 24172981, 2014). "Subsequently, using western blotting and qRT-PCR, the expression of LGR5 was assessed in three glioma cell lines U87, U118 and U251." (PMID 24172981, 2014). "The results showed that LGR5 was highly expressed in the three glioma cell lines when compared with that in the normal astrocytes; U87 cells were randomly used as an appropriate in vitro model for assessing LGR5 function in the subsequent experiments." (PMID 24172981, 2014). "In conclusion, our data demonstrated a correlation between LGR5 expression and the proliferation index in glioma, and knockdown of LGR5 resulted in suppression of glioma cell proliferation in vitro and in vivo." (PMID 24172981, 2014). "The expression levels of LGR5 mRNA and protein in several high grade glioma-derived cell lines (U118, U87 and U251) cultured in vitro were compared to the expression levels in normal human cultured primary astrocytes by western blot analysis and qRT-PCR." (PMID 24172981, 2014). "The mechanisms by which oncogenic mutations and alterations in signaling pathways lead to the upregulation of LGR5 protein expression is an important issue concerning glioma cells." (PMID 24172981, 2014). "To study the role of LGR5 in the malignant progression of glioma, we established a stably transfected U87 cell line expressing shRNA against LGR5." (PMID 24172981, 2014). "Glioma patients with high expression of LGR5 showed significantly poorer prognosis." (PMID 30208924, 2018). "Log-rank tests were performed to explore whether LGR5 expression level is significant with respect to the prognosis of glioma patients." (PMID 30208924, 2018). "The expression of LGR5 was detected in glioma parent cells and in enriched cells by FCM." (PMID 30208924, 2018). "A highly significant correlation between 5hmC β-value and gene expression was identified, raising the possibility that LGR5 expression in glioma may be regulated epigenetically by 5hmC." (PMID 29428975, 2018). "In addition, studies have shown that the expression of LGR5 is important for the cloning and tumorigenic abilities of glioma cells." (PMID 30208924, 2018). "Then, we explored the mechanism of glioma invasion and migration regulated by LGR5." (PMID 30208924, 2018). "The prognostic value of LGR5 in glioma need more evidence to confirm." (PMID 30208924, 2018). "In addition, IHC was performed to validate the role of LGR5 in the malignancy and invasiveness and stemness of glioma xenografts." (PMID 30208924, 2018). "LGR5+ glioma cells expressed stronger resistance to TMZ than LGR5− glioma cells." (PMID 30208924, 2018). "In addition, many glioma cells with both LGR5 and N-cadherin expression were observed in the invasive edge of human glioma tissues, while the internal tumor rarely expressed LGR5 and N-cadherin." (PMID 30208924, 2018). "LGR5 expression was determined in 268 glioma specimens by immunohistochemistry." (PMID 30208924, 2018). "In the present study, we found that LGR5 transcriptional levels were upregulated in gliomas." (PMID 24172981, 2014). "However, the exact mechanisms behind this transcriptional upregulation of LGR5 and its promotion of proliferation in glioma remain to be illuminated." (PMID 24172981, 2014). "Moreover, the effects of LGR5 knockdown by siRNA on glioma cell proliferation, cell cycle, clone formation and tumorsphere formation in vitro and gliomagenesis in vivo were assessed." (PMID 24172981, 2014). "In the present study, LGR5 protein was overexpressed in human glioma specimens." (PMID 24172981, 2014).